NOTCH1 (notch receptor 1)
Diseases named in the same sentence as NOTCH1 in open-access papers (continued):
Sharing a sentence is not in itself a finding about the gene and the disease.
chronic lymphocytic leukemia (continued). "NOTCH1 PEST domain mutations in chronic lymphocytic leukemia have recently been shown to be of prognostic relevance." (PMID 23734977, 2013). "In conclusion, NOTCH1 mutations were frequently detected in B cell CLL patients." (PMID 32458636, 2020). "Moreover, NOTCH1 mutated B cell CLL patients showed higher rate of relapse and mortality as compared with wild type CLL patients." (PMID 32458636, 2020). "However; NOTCH1 mutated B cell CLL cases showed longer PFS as compared with wild type CLL cases in fludarabine resistant patients who are on alemtuzumab therapy." (PMID 32458636, 2020). "Indeed, also in chronic lymphocytic leukemia, NOTCH1 mutations are subclonal in about 50% of cases with such mutations." (PMID 27566587, 2016). "Gain of function mutations of NOTCH1 have been reported in Chronic Lymphocytic Leukaemia (CLL)." (PMID 25711903, 2015). "Notch1 is also one of the most frequently mutated genes in chronic lymphocytic leukemia (CLL)." (PMID 25309874, 2014). "However, in chronic lymphocytic leukemia (CLL) cells with NOTCH1 mutations, RAC2 appears to function downstream of NOTCH signaling as inhibition of the NOTCH pathway with PF-03084014 leads to downregulation of RAC2 along with other genes involved in invasion and chemotaxis." (PMID 40072059, 2025). "The proto‐oncogene NOTCH1 is frequently mutated in around 10% of patients with chronic lymphocytic leukemia (CLL)." (PMID 29573199, 2018). "In chronic lymphocytic leukemia (CLL), NOTCH1 gene mutations (NOTCH1mut) have been associated with adverse prognostic features but the independence of these as a prognostic factor is still controversial." (PMID 27835908, 2016). "Accumulating evidence indicates a key role of deregulated NOTCH1 signaling in chronic lymphocytic leukemia (CLL)." (PMID 37817771, 2023). "Constitutive activation of NOTCH1-wild-type (NT1-WT) signaling is associated with poor outcomes in chronic lymphocytic leukemia (CLL), and NOTCH1 mutation (c.7541_7542delCT), which potentiates NOTCH1 signaling, worsens the prognosis." (PMID 37817771, 2023). "In humans, NOTCH1 and NOTCH2 function as recurrently mutated oncogenes in B cell lymphoproliferative disorders, including chronic lymphocytic leukemia and MZ lymphoma." (PMID 35579963, 2022). "In chronic lymphocytic leukaemia (CLL), recurrent NOTCH1 mutations were observed at all disease stages, whereas mutations in the paralogs NOTCH2, NOTCH3 and NOTCH4 were rare events with frequencies <1% (NOTCH2 in 0.9%; NOTCH3 in 0.7%; NOTCH4 in 0.6%)." (PMID 36313682, 2022). "Here the authors use retroviral transduction of primary malignant B cells from Chronic Lymphocytic Leukemia (CLL) and Mantle Cell Lymphoma (MCL) patients to show that NOTCH1/2-mutations facilitate mechanism of immune escape." (PMID 36266281, 2022). "Hyperactive Notch1 and Notch2 have been shown to sustain B cell Chronic lymphocytic leukemia (B-CLL)." (PMID 34394130, 2021). "Constitutive activation of Notch signaling is associated with chronic lymphocytic leukemia (CLL), with increased expression of NOTCH1, NOTCH2, JAGGED1, and JAGGED2." (PMID 34200313, 2021). "NOTCH1 aberrations frequently occur in hematological malignancies, mainly chronic lymphocytic leukemia and T-cell leukemia, making this gene a candidate target in the design of tailored therapy for this subtype." (PMID 33479306, 2021). "Cox regression analysis was conducted for prediction of OS within studied B cell CLL cases, using age, gender, BM lymphocytes, ALC, CD38, staging, NOTCH1 mutations as covariates." (PMID 32458636, 2020). "Notch 1, Notch 2 and their ligands Jag1 and Jag2 are constitutively expressed in B-cell chronic lymphocytic leukemia (CLL) and confer resistance to apoptosis in malignant B-cells." (PMID 33374160, 2020).
chronic lymphocytic leukemia (continued). "Cox regression analysis was conducted for prediction of LDT within B cell CLL patients, using age, gender, ALC, BM lymphocytes, staging, CD38, and NOTCH1 mutations as covariates." (PMID 32458636, 2020). "Cox regression analysis was conducted for prediction of PFS in B cell CLL patients, using age, gender, ALC, BM lymphocytes, staging, CD38, NOTCH1 mutations as covariates." (PMID 32458636, 2020). "In contrast, mutations in NOTCH1 (which encodes a trans-membrane receptor) reported to activate a cryptic splice site and resulted in an aberrant isoform of NOTCH1 in chronic lymphocytic leukemia (CLL)." (PMID 32481522, 2020). "To investigate chronic lymphocytic leukemia (CLL)-initiating cells, we assessed NOTCH1 mutation/expression in hematopoietic stem cells (HSCs)." (PMID 29732315, 2018). "As previously reported, chronic lymphocytic leukemia (CLL) cells show constitutive Notch1/2 activation and express the Notchligand Jagged1." (PMID 30478302, 2018). "NOTCH1 mutations occur in approximately 10% of patients with chronic lymphocytic leukemia (CLL)." (PMID 25633905, 2015). "Similarly, we also observe co-mutations characteristic of chronic lymphocytic leukemia (CLL); 6 out of 16 (37.5%) cases of trisomy 12 co-occurred with a mutation in NOTCH1, MYD88, or FBXW7; 2 out of 9 (22%) deletions on chr13q co-occurred with a ATM mutation." (PMID 33436578, 2021). "In fact, previous study has reported that NOTCH1 mutations were associated with lack of benefit of CD20 antibody therapies in chronic lymphocytic leukemia." (PMID 34956871, 2021). "Recently, transformation of chronic lymphocytic leukemia to diffuse large B-cell lymphoma (Richter ́s transformation) could be attributed in a comprehensive experimental setting relative to the activation of Akt signaling via Notch1." (PMID 34771672, 2021). "Interestingly, frequent non-mutational activation of NOTCH1 signaling has recently been demonstrated in B-cell chronic lymphocytic leukemia (B-CLL), significantly extending the pathogenic significance of this pathway in B-CLL." (PMID 29666622, 2018). "Of interest, NICD1 staining in chronic lymphocytic leukemia cells and in angioimmunoblastic lymphoma was consistently more pronounced in lymph nodes than in surrounding soft tissues, implicating factors in the nodal microenvironment in NOTCH1 activation in these diseases." (PMID 23825651, 2013). "In B-cell chronic lymphocytic leukemia (B-CLL), NOTCH1, NOTCH2, and their ligands (JAG1 and JAG2) are constitutively expressed." (PMID 35335147, 2022). "Alternative splicing of components of the Notch signaling system has been investigated extensively in the context of chronic lymphocytic leukemia (CLL), where Notch1 and 2, along with ligands Jagged1 and 2, are constitutively expressed." (PMID 35330188, 2022). "Genetic aberrations in Notch1 and Notch2 arise in B-cell neoplastic diseases such as Hodgkin lymphoma (HL), diffuse large B-cell lymphoma (DLBCL), chronic lymphocytic leukemia (CLL), follicular lymphoma (FL), and mantle cell lymphoma (MCL)." (PMID 31652497, 2019). "Instead, Notch1-activating mutations are present in 4-13% of B-cell chronic lymphocytic leukemia (B-CLL) cases, but nonmutational Notch1 activation has also been reported in B-CLL." (PMID 31346528, 2019).
chronic lymphocytic leukemia (continued). "In chronic lymphocytic leukemia (CLL), Notch1 and Notch2 signaling is constitutively activated and contributes to apoptosis resistance." (PMID 26041884, 2015). "Despite Chronic Lymphocytic Leukemia (CLL) patients, non-coding mutations in the Notch1 3’UTR have never been reported." (PMID 39684550, 2024). "Increased expression of CCND3 has also been observed in chronic lymphocytic leukaemia (CLL) cells, with RNA sequencing identifying a 38-fold increase in CCND3 in NOTCH1-mutated cells compared to NOTCH1 non-mutated cells." (PMID 37510349, 2023). "Moreover, we have found in the results that Notch-1 also performed an up-regulation in HTN, which was similar to that in chronic lymphocytic leukemia and T lymphocytes." (PMID 31343412, 2019). "In chronic lymphocytic leukaemia, Notch1 may represent a potential druggable target, suggesting that phytochemicals, such as EGCG and curcumin, may be beneficial in the treatment of chronic lymphocytic leukemia (CLL)." (PMID 39092224, 2024). "Interestingly, activating mutations affecting NOTCH1 are also present in 4–13% of B-cell chronic lymphocytic leukemia (B-CLL) cases, and very recently frequent non-mutational NOTCH1 activation in B-CLL has also been reported, irrespective of NOTCH1 mutational status." (PMID 29666622, 2018). "To address how NOTCH-mutations contribute to a dismal prognosis, we have generated isogenic primary human tumor cells from patients with Chronic Lymphocytic Leukemia (CLL) and Mantle Cell Lymphoma (MCL), differing only in their expression of the intracellular domain (ICD) of NOTCH1 or NOTCH2." (PMID 36266281, 2022). "Both NOTCH1 and NOTCH2 are constitutively activated in B-cell CLL but not expressed in normal B cells and may be involved in survival and resistance to apoptosis in CLL." (PMID 23734977, 2013). "Rosati E and co-workers demonstrated a high expression of Notch 1, Notch 2, JAG1 and JAG2, in malignant B-cells isolated from 25 patients affected by B-cell chronic lymphocytic leukemia (B-CLL) but not in normal B-cells." (PMID 33374160, 2020).
head and neck squamous cell carcinoma (58 papers, 2013 to 2026). A squamous cell carcinoma that arises from any of the following anatomic sites: lip and oral cavity, nasal cavity, paranasal sinuses, pharynx, larynx, and salivary glands. "Notch1, a tumor suppressor gene, is one of the most frequently mutated genes in head and neck squamous cell carcinoma (HNSCC)." (PMID 41026775, 2025). "For example, FBW7, an E3 ubiquitin ligase, interacts with SNX5 to reduce the ubiquitination and degradation of cancer-associated proteins such as c-Myc, NOTCH1, and Cyclin E1, thereby promoting the progression of head and neck squamous cell carcinoma (HNSCC)." (PMID 40144551, 2025). "Based on the efficacy signal seen in a patient with head and neck squamous cell carcinoma with a loss of function NOTCH1 mutation, a biomarker-driven strategy is now being pursued." (PMID 38539472, 2024). "NOTCH1 mutation is most common in lymphocytic leukemia, esophageal squamous cell carcinoma, and head and neck squamous cell carcinoma (HNCC), and it has been shown to be oncogenic." (PMID 36982170, 2023). "Two genome-wide association studies (GWAS) delineating the molecular mechanisms underlying head and neck squamous cell carcinoma (HNSCC) have identified inactivating mutations in Notch1, suggesting a tumor-suppressing function of Notch in this disease." (PMID 37255594, 2023). "Specifically, NOTCH1 mutation has been proven to be associated with invasion and metastasis in advanced head and neck squamous cell carcinomas (HNSCC)." (PMID 35911687, 2022). "Genetic alterations in NOTCH1 were associated with a high mean grade of radiation-induced toxicity in head and neck squamous cell carcinoma." (PMID 35837112, 2022). "Of relevance, loss-of-function mutations of the NOTCH1 gene have been detected in about 10% of head and neck squamous cell carcinoma (HNSCC), making it one of the most mutated genes in squamous cell carcinoma, which is highly associated with smoking." (PMID 30744164, 2019). "A comprehensive analysis of multiple head and neck squamous cell carcinoma (HNSCC) datasets demonstrated that 10–15% of HNSCC harbour inactivating NOTCH1 mutations." (PMID 31827722, 2019). "Mutations in Notch1 are also associated with many other diseases, such as aortic valve disease, head and neck squamous cell carcinoma, and breast cancer." (PMID 28415716, 2017). "Many NOTCH1 driver mutations have been reported in hematopoietic tumors, head and neck squamous cell carcinoma and other malignancies." (PMID 25803323, 2015). "The frequency of NOTCH1 mutations is about 5% and is thus considerably lower than in head-and-neck squamous cell carcinomas." (PMID 25167871, 2014). "Notch1 is a very large gene (34 exons) that shows several inactivating mutations, suggesting it may function as a tumor suppressor gene in squamous cell carcinomas of the head and neck (HNSCCs)." (PMID 30004402, 2018). "Inactivating NOTCH1 mutations in head and neck squamous cell carcinoma (HNSCC) were described over a decade ago, suggesting a tumor suppressor function - unlike its oncogenic role in other tumors." (PMID 41989846, 2026). "Recently published new-generation sequencing studies in head and neck squamous cell carcinoma (HNSCC) have unveiled prominent roles in carcinogenesis and cell invasion of mutations involving NOTCH1 and PI3K-patwhay components." (PMID 25836654, 2015).
head and neck squamous cell carcinoma (continued). "NOTCH1-induced stemness promotes the resistance to chemotherapy or radiotherapy in head and neck squamous cell carcinomas cells." (PMID 36119057, 2022). "NOTCH1 is, therefore, most likely involved in migration and proliferation of head and neck squamous cell carcinoma and is a prognostic marker in these patients." (PMID 35205828, 2022). "By conducting a database search, we found that another two tumor suppressor genes, NOTCH1 and FAT1, have a high nonsense mutation rate in head and neck squamous cell carcinoma (HNSCC)." (PMID 36428516, 2022). "In addition, a high prevalence of inactivating mutations in NOTCH1 have been identified suggesting a tumor-suppressive role of Notch signaling in head and neck squamous cell carcinomas (HNSCC) in general and OSCC in particular." (PMID 32957697, 2020). "Regarding the membrane receptor Notch1, a recent paper demonstrated that Notch1 loss of function increases the sensitivity to PI3K/mTOR pathway inhibitors in in vitro head and neck squamous cell carcinoma." (PMID 33266496, 2020). "Previous study indicates that Notch1 regulates metastasis of head and neck squamous cell carcinoma by inducing EMT." (PMID 31477177, 2019). "Notch1 was reported to regulate invasion and metastasis of head and neck squamous cell carcinoma by inducing EMT through c-myc42." (PMID 30679629, 2019). "This study was aimed to investigate the possibility of targeting head neck squamous cell carcinoma (HNSCC) by NOTCH1 pathway inhibition and explore the synergistic effect of combining NOTCH inhibition with conventional chemotherapy." (PMID 27108536, 2016). "In summary, our findings suggest that inhibition of SUV39H1 in head and neck squamous cell carcinoma may affect angiogenesis by regulating Notch1 expression." (PMID 38650654, 2024). "Recently, two studies hypothesized that Notch1 has a tumor-suppressive function in head and neck squamous cell carcinoma (HNSCC)." (PMID 24179495, 2013). "PI3K/mTOR inhibition leads to apoptosis of NOTCH1-mutant head and neck squamous cell carcinoma (HNSCC) cells." (PMID 36124629, 2022). "Compared to the other types of cancers, NOTCH1 and FAT1 have a relatively high nonsense mutation rate in head and neck squamous cell carcinoma (HNSCC)." (PMID 36428516, 2022). "We investigated the correlation between NOTCH1 and CD31 expression in head and neck squamous cell carcinoma in the GEPIA database and found that the expression of NOTCH1 was positively correlated with that of CD31." (PMID 38650654, 2024). "It is also reported that a cleaved form of Notch1, NICD promoted the self-renewal capacity of CSCs in head and neck squamous cell carcinoma by activating sphere formation and increasing the expression of stem cell markers." (PMID 33959615, 2021). "There is evidence that overexpression of c-fos in head and neck squamous cell carcinoma enhances epithelial-mesenchymal transition (EMT) and the expression of cancer cell markers (Nanog, c-Myc, Sox2 and Notch1)." (PMID 33096691, 2020). "Moreover, HES1 has been found to be overexpressed in 32% of head and neck squamous cell carcinomas (HNSCC), but only in the absence of NOTCH1-inactivating mutation." (PMID 41009728, 2025).
head and neck squamous cell carcinoma (continued). "Notch1 also appears to critically regulate stemness in head and neck squamous cell carcinoma (HNSCC) cells, as constitutive activation of NICD in HNSCC cells promotes self-renewal by enhancing tumorsphere formation and upregulating stemness markers such as OCT4, SOX2, and CD44." (PMID 36118530, 2022).